PCNA (proliferating cell nuclear antigen)
Diseases named in the same sentence as PCNA in open-access papers (continued):
Sharing a sentence is not in itself a finding about the gene and the disease.
lung carcinoma (72 papers, 2011 to 2025). "In a study on the underlying molecular mechanism of TQ on A549 lung cancer cell line, it was revealed that incubation of A549 cells with TQ reduced the expression of proliferating cell nuclear antigen (PCNA) as a proliferation marker, as well as cyclin D1." (PMID 35236304, 2022). "There were 5 studies (202 patients) which investigated associations between 18F-FDG PET and PCNA in lung cancer." (PMID 29983647, 2018). "In addition, proliferating cell nuclear antigen-normalized mRNA expression of DPYD has previously been reported to be associated with sensitivity to CDDP in lung cancer tissues." (PMID 23420099, 2013). "Although KCTD10 has been reported to interact with PCNA in A549 lung cancer cells, its precise function and molecular mechanisms in lung cancer are elusive." (PMID 40873559, 2025). "For instance, in breast and lungcancer, high PCNA levels were associated with WNT pathway alterations,whereas altered mTOR signaling was associated with high pCNA levelsin breast, ovarian, and lung cancers." (PMID 40657100, 2025). "PCNA, as a marker of proliferation in cancer, is highly up-regulated in lung cancer and closely relevant with the prognosis." (PMID 38554175, 2024). "MJs, particularly MJ5, immunohistochemically decreased lung cancers with a PCNA-positive index (proliferating cell nuclear antigen)." (PMID 37109466, 2023). "In vitro, T4 at physiologic free hormone concentrations and T3 at supraphysiologic concentrations stimulated cell proliferation and increased PCNA abundance in lung cancer cells." (PMID 37014291, 2023). "The results of immunohistochemical testing showed that, compared to the lung cancer group, the protein expression of the tissue cell proliferation markers PCNA and KI67 in the Exos group was reduced." (PMID 36643646, 2023). "Overexpression of PCNA is observed in lung cancer in vitro and in vivo, while silencing of PCNA reduces cell invasion ability and 95D cells proliferations." (PMID 36776764, 2023). "The current data attributed the decrease in the viability of A549 cells after CPO treatment to the decrease in Ki-67 and PCNA expressions, signifying its chemotherapeutic effectiveness on lung cancer." (PMID 37233859, 2023). "In consistence with previous report, TIM-4 overexpression promoted proliferating cell nuclear antigen (PCNA), Cyclin A2, Cyclin B1 expression in lung cancer cells." (PMID 36806050, 2023). "The function of PCNA in lung cancer was found to be regulated by miRNA, which promotes the growth and proliferation of tumor cells, and PCNA is a potential therapeutic target." (PMID 35884433, 2022). "Expression levels of hub genes were also positively correlated with the Ki-67 and PCNA expression (proliferation markers), which was in agreement with the opinion that hub genes were key factors in lung cancer cell proliferation." (PMID 36176446, 2022). "Ganoderan B (GDNB), a component of GLP, repressed the proliferation of lung cancer cells by downregulating Ki67 and proliferating cell nuclear antigen (PCNA)." (PMID 35865946, 2022). "Mxi1 or KLF9 elevation or miR-300 repression inhibited lung cancer cell proliferation, as evidenced by reduced Ki67 and PCNA expression, and lowered invasion and migration." (PMID 35501353, 2022). "A study showed that overexpression of PCNA promotes cell proliferation and tumorigenesis in lung cancer." (PMID 33272232, 2020). "Both BRCA1 and PCNA are critical regulators for DNA replication and repair, whose potential to act as prognostic indicators in lung cancers have been well-documented." (PMID 33097805, 2020). "Among several cell cycle regulatory proteins, the expression of CDK2 and PCNA was dramatically decreased in the lung tumor tissues of parkin KO mice compared with that in WT mice and parkin siRNA-transfected lung cancer cells." (PMID 31112565, 2019). "MiR-363-3p has been reported to suppress the specific target gene PCNA to exert an anti-proliferation effect on lung cancer cells." (PMID 31297133, 2019).
lung carcinoma (continued). "We determined the combinatorial effects of PCNA-I1S with cisPt on growth inhibition in lung cancer cells." (PMID 31600334, 2019). "The purpose of this study was to investigate the combinatorial effects of lead compound PCNA-I1S with DNA damaging agents on cell growth, DNA damage, and DNA repair in four lines of human prostate and lung cancer cells." (PMID 31600334, 2019). "With MTS, we analyzed the silencing of TM4SF1 on cell viability and cell growth in lung cancer cell lines, by western blot,the PCNA expression was downregulated by knocking down TM4SF1." (PMID 31142317, 2019). "We discovered that many lncRNAs were located nearby important key regulators of lung cancer, including FN1, PCNA, BUB1, GNB1, and other cancer associated genes." (PMID 26918601, 2016). "Expression of S100A4, PCNA and c-fos were reduced in STAT1- and STAT1-CC-expressing lung cancer cells, while PCNA and c-fos were decreased to a greater extent in STAT1-CC cells." (PMID 26351076, 2015). "S100A4 is associated with increased cell growth and metastatic capacity of lung cancer cells, and, PCNA plays an important role in DNA replication and repair." (PMID 26351076, 2015). "In other terms, our data suggest that the global DNA hypomethylation induced by the disruption of DNMT1/PCNA interactions acts such as an oncogenic event of the brain, breast, mesothelial and lung cancers." (PMID 24637615, 2014). "A previous study has shown that KCTD10 interacts with proliferating cell nuclear antigen, and increases DNA synthesis and proliferation of lung cancer cells." (PMID 23977394, 2013). "Next, to investigate whether DEE‐OEs‐induced cell transformation resembles the process of lung tumorigenesis, we analyzed the expression of lung cancer‐related proteins, including PCNA, PTEN, AKT, and ERK pathways." (PMID 40583191, 2025). "Additionally, ZBED3 promotes lung cancer cell proliferation by regulating the expression of proliferating cell nuclear antigen." (PMID 38182896, 2024). "PCNA serves as a moving platform that allows DNA- and chromatin-interacting proteins to operate at the fork in a DNA sequence-independent manner, and targeting PCNA-1 can inhibit the proliferation of lung cancer cells." (PMID 38519533, 2024). "WB protein level detection further verified that the expression levels of lung cancer cell proliferation–related proteins PCNA and KI67 and anti-apoptotic protein Bcl-2 were significantly decreased after adding Exos, but the expression of pro-apoptotic protein Bax was increased." (PMID 36643646, 2023). "Moreover, the correlation of Ki67 and PCNA in cancer cell proliferation has been documented, specifically in the context of lung cancer progression." (PMID 35501353, 2022). "Our study not only confirmed their findings but also furthered our understanding of the role of Mxi1 in the pathogenesis of lung cancer, by demonstrating that Mxi1 elevation inhibited tumor cell proliferation as evidenced by reduced Ki67 and PCNA levels, and lower invasion and migration." (PMID 35501353, 2022). "Indeed, we found that PCNA expression was also significantly increased in lung cancer patients’ tumors from TCGA datasets and the GEO database." (PMID 35884433, 2022). "Regarding the lung cancer model, increased expression of markers of cell proliferation like proliferating cell nuclear antigen (PCNA) and ERK1/2 activation which play an important role in the pathogenesis of lung cancer is associated with increased expression of T3 and/or T4." (PMID 33846395, 2021). "Furthermore, overexpressed PCNA promotes cancer cell growth, colony formation and tumorigenesis of lung cancer cells, and suppresses the apoptosis of cancer cells." (PMID 33194611, 2020). "Our data show that the combination of PCNA-I1S with DNA damage agents Cs-137 irradiation, UV-C irradiation, or cisPt produced significant additive effects on cell growth inhibition and DNA damage, and PCNA-I1S attenuated DNA repair in human prostate and lung cancer cells." (PMID 31600334, 2019).
lung carcinoma (continued). "Thus, we investigated the expression of PCNA and other cell cycle regulatory proteins in lung tumor tissues and lung cancer cell lines by immunoblotting after treatment with parkin siRNA." (PMID 31112565, 2019). "NF-κB in lung cancer cells is responsible for the induction of several anti-apoptotic and pro-proliferative proteins, as well as inflammatory factors, including Bcl-XL, Bcl-2, PCNA, and IL-6." (PMID 27602766, 2016). "Four nGGOs diagnosed as benign lesions and another four nGGOs with non-diagnostic results on PCNA or PCNB underwent surgical resection based on strong clinical suspicion for lung cancer, and were demonstrated to be invasive adenocarcinomas." (PMID 25406492, 2014). "Furthermore, PCNA together with cyclin D1 could be significantly decreased with miR-107 ectopic expression in lung cancer cells and colorectal cancer cells, suggesting that miR-107 was an important regulator of cell proliferation." (PMID 33981849, 2021). "The objective of the present study was to further investigate the effects of PCNA-I1S alone or in combination with several types of DNA damaging agents on cell growth inhibition, DNA damage, and to evaluate the effects of PCNA-I1S on DNA repair in prostate and lung cancer cells." (PMID 31600334, 2019). "In addition, PCNA mRNA levels were only moderately increased (1.4-fold) in lung cancer compared to those of Claspin and CHK1 (4.5- and 4.4-fold, respectively), indicating that the increased expression of Claspin, Timeless, and CHK1 in cancer cells does not simply reflect increased proliferation." (PMID 30796221, 2019). "The involvement of PPARβ/δ in lung cancer was first reported in an in vitro study showing that the agonist L-165041 induces growth inhibition of A549 cells, as evidenced by decreased expression of the proliferation marker proliferating cell nuclear antigen (PCNA)." (PMID 28316613, 2017). "In the A549 lung cancer cell line, TQ treatment was shown to downregulate cyclin D1, MMP2, MMP9, and PCNA (proliferating cell nuclear antigen)." (PMID 41303508, 2025). "Based on tumour cellularity, Ki‐67 positivity and proliferating cell nuclear antigen (PCNA), together with clinical stage and histological differentiation, provided additional useful information for predicting lung cancer evolution and prognosis." (PMID 38286746, 2024). "An experiment was conducted on human lung carcinoma A549 cells (CRM-CCL-185TM) treated with PTX, and after 48 h, the cells were processed with a PCNA antibody to analyze antigen expression." (PMID 39062149, 2024). "In lung cancer mouse models, Melittin achieved tumor suppression by selectively targeting and reducing VEGF, PCNA, and CD31 (an angiogenesis marker) within the tumor cells." (PMID 38732255, 2024). "At the molecular level, SCFAs derived from the microbiome inhibit the growth of various cancers, such as colon and lung cancer, by modulating GPCRs, histone hyperacetylation, or through the dysregulation of the expression of BCL-2 and PCNA." (PMID 37564290, 2023). "In REV1-silenced lung cancer cells, the expression level of SERTAD2 was significantly reduced, and the expression levels of Rad18, mUb-PCNA and RPA32 were also reduced to varying degrees." (PMID 35115490, 2022). "In agreement with SOD1 as a key factor for lung cancer cell proliferation, SOD1 level was also positively correlated with that of PCNA, a proliferation marker, Moreover, NSCLC tumors with high SOD1 expression correlated with poor survival." (PMID 33859191, 2021).
lung carcinoma (continued). "We also observed that p21 directly interacts with CDK2 or PCNA, and the interaction between p21/CDK2 or p21/PCNA following parkin siRNA treatment was increased in A549 lung cancer cell lines." (PMID 31112565, 2019). "Moreover, the data suggest that targeting PCNA with these PCNA inhibitors may provide a novel approach for enhancing the efficacy of chemotherapy and radiation therapy in treatment of human prostate and lung cancers." (PMID 31600334, 2019). "Tumor proliferation and apoptosis in VX2 orthotopic lung cancer rabbits were confirmed by TUNEL, PCNA assay and flow cytometry after treatment with DTX-IN, DTX-LP, or saline." (PMID 28855665, 2017). "Among them, CTNNB1, ZEB1, CDC42, HSP90AA1, BST2, PCNA, and E2F1 have all been shown to promote lung cancer progression, while SAMHD1, HRAS, and NQO1 serve as tumor suppressor genes." (PMID 28498804, 2017). "To further elucidate the role of CXCL16-CXCR6 axis in lung cancer, we also observed the action of CXCL16 on PCNA (proliferating cell nuclear antigen) expression and invasive ability of A549, H292 and 95D cells." (PMID 24897301, 2014). "The results showed expression of Ki67 and PCNA revitalized with the treatment of DHA and NRAS plasmid compared with DHA treatment alone, suggesting that recovery of NRAS molecule abolished DHA-driven anti-lung cancer proliferation." (PMID 38778121, 2024). "Immunohistochemical staining of tumors showed that 25HC had no inhibitory effect on proliferation of lung cancer (PCNA, whereas 25HC plus gilteritinib reduced the number of PCNA-positive cells." (PMID 39349433, 2024). "Anti-integrin αvβ3 antibodies, but not anti-integrin αvβ5 antibodies, were demonstrated to abrogate the T4-induced PCNA accumulation in both NCI-H522 cells and NCI-H510A cells, indicating integrin αvβ3 as mediator of T4-induced PCNA accumulation in lung cancer cells." (PMID 35008863, 2021). "In lung cancer, TM4SF1 significantly regulated PCNA and reduced the viability of lung cancer cells." (PMID 33015133, 2020). "BPDE treatment of lung cancer cells results in ATR/Chk1-mediated recruitment of Pol κ via Rad18 and the subsequent monoubiquitination of PCNA, and inhibition of ATR/Chk1 signaling prevents the interaction between Pol κ and PCNA." (PMID 30347795, 2018). "Confirmation of the effects of T4 and T3 on PCNA was obtained in thymidine incorporation studies in non-small cell NCI-H522 lung cancer cells as well as in small cell NCI-H510A cancer cells." (PMID 22132110, 2011). "We compared the expression of candidate target genes between lung cancer tissues and adjacent non-cancerous lung tissues from 50 patients and determined that the PCNA was expressed at higher levels in lung cancer tissues than in adjacent non-cancerous lung tissues." (PMID 28423618, 2017). "Since fibronectin, β-catenin, S100A4, proliferating cell nuclear antigen (PCNA) and c-fos have been reported to be involved in the control of cell growth or metastasis in cancers, we also evaluated the effect of STAT1-CC on the expression of these proteins in lung cancer cells." (PMID 26351076, 2015). "Elevated expression of SETD8 stimulated S-phase progression via methylating a non-histone protein proliferating cell nuclear antigen (PCNA), thus promoted proliferation of lung cancer cells." (PMID 30002791, 2018). "A proteomics analysis study suggests that the expression of cytokeratine 8, Y-box binding protein 1 (YB-1), proliferating cell nuclear antigen (PCNA), non-metastatic protein 23 (Nm23) were also significant in lung cancer development." (PMID 26061816, 2015).